SMAD4 (SMAD family member 4)
Diseases named in the same sentence as SMAD4 in open-access papers (continued):
Sharing a sentence is not in itself a finding about the gene and the disease.
tumor (continued). "A second important aspect is relative to the role of the SMAD4 in tumor formation either as an epithelial 'gatekeeper' or as a 'landscaper', that is, acting from within the microenvironment to affect epithelial homeostasis." (PMID 19014666, 2008). "To confirm the validity of our study, we showed similar frequencies of loss of PTEN and SMAD4 expression in our PDAC samples, and higher levels of ADAM9 and βCAT in tumor compared with normal ducts as previously reported." (PMID 18254976, 2008). "Among the remaining hub genes, the eya-1 mammalian orthologs promote development of tissues and organs whereas the sma-4 ortholog SMAD4/DCP4 acts as a tumor suppressor." (PMID 18752680, 2008). "This cell model proved that reexpression of Smad4 at subphysiological levels was adequate to suppress tumor growth whereas TGFβ resistance of the cells was retained." (PMID 18664273, 2008). "In this study we have shown that haploinsufficiency at the SMAD4 tumor suppressor locus underlies polyp formation in a proportion of GI tumors from JPS patients, as previously shown in Smad4-mutant mouse models." (PMID 19014666, 2008). "From our own IHC analysis, it should be evident that the SMAD4 expression pattern in the tumor microenvironment appears rather heterogeneous, with a mixture of positive and negative stromal fibroblasts and infiltrating lymphocytes." (PMID 19014666, 2008). "Functional inactivation of the tumor suppressor Smad4 in colorectal and pancreatic carcinogenesis occurs coincident with the transition to invasive growth." (PMID 18664273, 2008). "SMAD4 showed a low positivity in 9 (36%) cases, with 60–80% of the tumor cells exhibiting immunoreactivity and the other additional 11 (44%) cases showed a high positivity with 40–90% of the tumor cells exhibiting immunoreactivity." (PMID 17587453, 2007). "Nuclear expression in the stroma was detected in 46% (143 of 310) of tumours for Smad3 and 97% (301 of 309) for Smad4." (PMID 17692120, 2007). "Smad4 is a tumour suppressor gene primarily known for its frequent inactivation in gastrointestinal malignancies." (PMID 17997817, 2007). "Briefly, SMAD4 (DPC4) is a tumor-suppressor gene located on chromosome 18q which has been shown to mediate the downstream effects of TGF-β superfamily signaling, resulting in growth inhibition." (PMID 17587453, 2007). "Smad4-mediated tumour suppression in vivo was apparent at physiological expression levels as well as in Smad4 overexpressing clones." (PMID 17997817, 2007). "The region of 18q21.2–q22.1 harbours 16 candidate genes in addition to SMAD4 (18q21.1) that is one of the most recurrently inactivated tumour suppressor genes in PDAC." (PMID 17242705, 2007). "In order to assess the scope of our findings we wished to know if Smad4 controls the expression of secreted TGF-β target genes in tumour cells derived from other organs." (PMID 17997817, 2007). "Reduction of tumour growth in nude mice was observed in clones with either physiological or high Smad4 expression levels." (PMID 17997817, 2007). "The ability of Smad4 to mediate tumour suppression has largely been attributed to its presumed role as a mediator of TGF-β-induced growth inhibition." (PMID 17997817, 2007). "The prevailing view suggests that the tumour suppressor function of Smad4 primarily resides in its capability to mediate TGF-β growth inhibitory responses." (PMID 17997817, 2007). "In the majority of tumours (nuclear or cytoplasmatic) expression of Smad3 (91%; 279 of 309 tumours) and Smad4 (100% or all 305 tumours) was found." (PMID 17692120, 2007). "In particular, SMAD4 (DPC4), present in 18q21.1 and encoding a downstream signal transducer of TGF-β (transforming growth factor-β), has been implicated as an important tumor suppressor lost by 18q deletion." (PMID 17474983, 2007). "Defining the mechanisms of Smad4 tumour suppressor function and identifying Smad4 target genes is critical to address its potential as a therapeutic or diagnostic target." (PMID 17997817, 2007).
tumor (continued). "Restoration of some TGF-β responsiveness was restricted to clones displaying 20- to 50-fold overexpression of Smad4, while physiological Smad4 levels were capable of exerting a Smad4-mediated reduction in tumour growth." (PMID 17997817, 2007). "In a previous study, the genomic inactivation of Smad4 was reported to correlate with carcinogenesis, tumour progression and poorer prognosis in colorectal caners." (PMID 17088901, 2006). "Analysis of survival time of Smad4-positive and Smad4-negative patients stratified with regard to tumor stage, ER-status, TβRI-status, and TβRII-status." (PMID 16438724, 2006). "A dot blot set up with serial dilutions of total protein extracts from tumor tissues as well as MCF-7 cells showed decreasing signal intensities with decreasing Smad4-concentrations." (PMID 16438724, 2006). "Smad4 protein, whose gene is coded at chromosome 18q21.1, is an important tumour suppressor that mediates transforming growth factor-beta." (PMID 17088901, 2006). "The tumour suppressor Smad4 is required during gastrulation and later in the anterior development of the mouse embryo as shown by the Smad4 knockout mouse." (PMID 16611366, 2006). "In our specimens, Smad4 expression in tumor tissue was lower than in surrounding epithelia, indicating impaired TGF-β signaling and possible escape from TGF-β-dependent growth inhibition." (PMID 16438724, 2006). "In general, Smad4 immunostaining was stronger in the surrounding normal breast epithelia than in tumor tissues." (PMID 16438724, 2006). "Among the 294 tumours for which gene dosage data (Smad2, Smad4 and DCC) were available, 167 tumours (57%) showed heterozygous loss of Smad4, and 73 out of 167 samples were randomly chosen for mutation analysis." (PMID 12569386, 2003). "Within the individual tumours in this statistical analysis, the frequency of SMAD4 gene deletion was 67% (135 out of 202)." (PMID 12237773, 2002). "Activation of TGF-β receptor type I (RI) and RII by TGF-β induces nuclear translocation of Smad proteins including Smad2 and Smad4 that have been originally identified as tumour suppressor genes." (PMID 10789724, 2000). "Importantly, the differentially expressed SMAD4 targets in the liver and lungs included genes that distinguish between SMAD4’s tumor-suppressive and tumor-promoting functions." (PMID 40999053, 2025). "More broadly, our analysis reveals discordant engagement of Smad4’s tumor-suppressive versus tumor-promoting effectors in liver versus lung metastases, demonstrating that the anatomic site of the tumor can uncouple TGFβ’s antitumorigenic and protumorigenic programs." (PMID 40999053, 2025). "The protein expression of SMAD4 was upregulated in the tumor tissues of the AMDHD1-OV group." (PMID 39143229, 2025). "Further, we show a tumor-suppressive role for SMAD4 in OSCC cells." (PMID 40338154, 2025). "Furthermore, contrary to TGFBR2 loss, SMAD4 deletion in KPC and KvPC PDAC drove primary tumor growth in vivo." (PMID 39841099, 2025). "Furthermore, neutrophils exposed to soluble factors derived from SMAD4-deficient CRCs exhibit upregulated CXCL8 expression, thereby amplifying the inflammatory signaling within the tumor microenvironment." (PMID 40943634, 2025). "Collectively, these results underscore the tumor-suppressive role of SMAD4 in OSCC cells." (PMID 40338154, 2025). "SMAD4 is a tumor suppressor involved in the TGF- β signaling pathway." (PMID 40647527, 2025).
tumor (continued). "Moreover, a smaller number of driver mutations and deletions in tumor suppressor genes (for example, KEAP1 and SMAD4) were also significantly associated with high clone proliferation, matching results in previous cell line small interfering RNA experiments." (PMID 39614124, 2025). "SMAD4 IHC staining was intact in the other tumor sites and control groups." (PMID 40487260, 2025). "Given the dual role of TGF-Beta as both a tumor suppressor and a pro-oncogenic factor, further studies are needed to explore whether SMAD4 alterations contribute to differential disease progression between ethnic groups." (PMID 40227587, 2025). "Furthermore, our results indicate that the METTL3/miR-146a-5p mediated oncogenic effect in OSCC is via direct targeting of SMAD4, a well-known tumor-suppressor gene, by miR-146a-5p." (PMID 40338154, 2025). "Enriched in PC3-ML cells, exosomal miR-888 downregulates important proteins such as Krüppel-like factor 5 (KLF5), retinoblastoma-like protein 1 (RBL1), tissue Inhibitor of metalloproteinases 2 (TIMP2), and SMAD family member 4 (SMAD4), enhancing overall tumor cell capabilities." (PMID 40556678, 2025). "However, phosphorylated SMAD4 protein can attenuate this tumor-suppressive function and accelerate pancreatic tumorigenesis." (PMID 40619414, 2025). "Other tumor suppressors commonly inactivated in radioresistant tumors include SMAD4 and PTEN." (PMID 40725389, 2025). "Prior studies suggest that TGF-β-mediated EMT induction may depend on Smad4 deficiency, as Smad4 inactivation impairs TGF-β-induced apoptosis and tumor-suppressive effects." (PMID 41472816, 2025). "SMAD4 loss itself, thus, does not universally favor tumor growth because its inactivation appears to be a liability rather than an advantage for lung metastases, at least in the clinically relevant setting of preseeded metastases modeled in our study." (PMID 40999053, 2025). "Upon Smad4 reactivation, liver metastases expressing shRen and shRunx1 continued to show a reduction in tumor burden consistent with SMAD4-mediated tumor suppression, whereas those expressing shKlf4 now exhibited a threefold increase in metastasis burden, akin to the behavior of lung metastases." (PMID 40999053, 2025). "PC3-ML cells contain high levels of exosomal miR-888, which downregulates proteins such as Krüppel-like factor 5 (KLF5), retinoblastoma-like protein 1 (RBL1), tissue Inhibitor of metalloproteinases 2 (TIMP2), and SMAD family member 4 (SMAD4), strengthening tumour cell abilities." (PMID 41465110, 2025). "Consistent with its organ-specific effects on tumor growth, Smad4 restoration led to upregulation of partially overlapping but mostly distinct genes, as compared to tumor cells kept on Dox: 89% (1,580/1,773) and 74% (613/825) organ-specific genes on days 7 and 14, respectively." (PMID 40999053, 2025). "SMAD4, a known tumor suppressor, plays a central role as a mediator in the TGF-β signaling pathway." (PMID 40277937, 2025). "For instance, a stop gained variant was detected in the APC gene in plasma samples from M01 and a missense variant was detected in SMAD4 in plasma samples from patient M25, neither of which were detected in matched tumor tissue." (PMID 41044171, 2025). "Besides, SMAD4 deficiency induces the upregulation of the glycolytic enzyme PGK1 in PDAC, which enhances tumor glycolytic activity and influences tumor progression and invasion." (PMID 40619414, 2025). "However, a tumor‐suppressive effect of TGF‐β1 was evident in most of the primary SMAD4 wild‐type PDTs in basal medium (PDT2‐5), while lines carrying mutations in the TGF‐β signaling pathway were less sensitive to TGF‐β1 treatment (PDT6,7,8)." (PMID 40066744, 2025).
tumor (continued). "designed two circular staple RNAs with multiple intermittently spaced binding sites that recognize different segments of mRNA expressing Smad4, a tumor‐suppressing gene; the two circular RNA strands and single‐stranded mRNA self‐assemble to form a 3D lantern‐shaped nanostructure." (PMID 39263835, 2025). "The lung-into-liver swap abrogated SMAD4’s tumor-suppressive response in the liver, while the liver-into-lung swap impaired SMAD4’s tumor-promoting response in the lung, which was reflected in the unchanged tumor burden and fractions of Ki67+ and p57+ cells upon Smad4 restoration in both organs." (PMID 40999053, 2025). "While we were unable to assess longer-term effects on fibrosis because of the limited time between reliable metastasis detection and humane endpoint, these data validate in an autochthonous model the discordance of a key Smad4 output that underpins its organ-specific tumor phenotypes." (PMID 40999053, 2025). "Consistent with results from conventional knockout GEMMs16,18–20, Smad4 depletion (by continuous Dox administration starting at 5 weeks of age) promoted tumor initiation, shortened survival and led to the development of tumors that metastasize to the liver and, less frequently, to the lungs." (PMID 40999053, 2025). "Alternatively, Smad4 may exert its tumor-suppressive effects indirectly through dysregulation of cell cycle control or aberrant proliferative pathways." (PMID 40980689, 2025). "Notably, knockout of known tumor suppressors SetD2 and Smad4 maintained normal tumor growth, confirming the specificity of our approach." (PMID 41472851, 2025). "SMAD4 was the predominant mutation in early stages (I–II) (56.0% vs. 26.5%, p = 0.021), while later stages (III–IV) showed significantly higher rates of KRAS mutations (100.0% vs. 75.8%, p = 0.001) compared to PHC at corresponding tumor stages." (PMID 40507259, 2025). "Of note, these observations were specific to Smad4 restoration and not a general effect of p57 knockdown on proliferation, as p57 depletion did not affect baseline tumor burden or the fraction of Ki67+ tumor cells in the Smad4-deficient condition." (PMID 40999053, 2025). "This study showed that the loss of Smad4, a frequent event linked to the progression of PDA, disables TGF-β1-sensitive PDA cells from their normal fate of undergoing a lethal program of EMT towards promoting tumor growth." (PMID 38675493, 2024). "This study suggests that SMAD4 Y353C may act as a tumor suppressor gene, emphasizing its potential as a therapeutic target and the need for further research to explore its mechanisms and implications for PDAC treatment." (PMID 38666907, 2024). "Loss of SMAD4 does not change the growth rate of the primary tumor, but plays a direct role in promoting metastasis." (PMID 38329726, 2024). "As Smad4 is normally inactivated in PDAC and Smad4 deficiency promotes lactate formation, a slight upregulation of the tumor suppressor PDAC + DM points to presumably lower invasiveness and metastasis of the tumor in patients with PDAC+ DM." (PMID 39123454, 2024). "Knockdown of IBSP cells suppressed the SMAD4 induced growth of tumor cells." (PMID 39118232, 2024).
tumor (continued). "While SMAD4 mutation abundance in tumor was not significantly prognostic, high SMAD4 mutation abundance in ctDNA was significantly associated with poorer survival (OS, P < 0.001; PFS, P < 0.001)." (PMID 38378604, 2024). "However, a tumor-promoting effect of BMP4 is reported in other tumor types, especially when SMAD4 is inactive." (PMID 38689334, 2024). "SMAD4 is a tumor suppressor gene that mediates the TGFβ signaling pathway leading to apoptosis." (PMID 38975412, 2024). "The SMAD4 protein is part of the TGF-β pathway which is considered a tumor suppressor." (PMID 40458305, 2024). "Several miRNAs that are predicted to interact with SMAD4-213 have a tumor-suppressive role in CRC and the sponging function of SMAD4-213 may disable that role." (PMID 39132157, 2024). "Our results show that si‐IBSP could rescue SMAD4‐induced cell metastasis, proliferation, and inhibit tumor progression, which contributes to the treatment and prognosis of patients." (PMID 39118232, 2024). "Additionally, knockout of Smad4 in a PDAC mouse model has increased tumor sensitivity to host immune control and induced DNA damage." (PMID 38500662, 2024). "Smad4 knockout in myeloid cells significantly promoted tumor growth." (PMID 39664586, 2024). "Research on CRC indicates that the molecular characteristics of the cancer are significantly related to location of the tumor, which may indirectly influence the relationship between SMAD4 deletion and the development of CRC." (PMID 39164192, 2024). "In addition, arctiin has been shown to slow down tumor fibrosis by decreasing the expression of two proteins, β-catenin and SMAD4." (PMID 38205087, 2024). "In addition, W. coagulans MZY531 regulates the Bax/Bcl-2/caspase-3 and JAK2/STAT3 apoptosis pathways and PI3K/AKT/mTOR pathways, as well as TGF-β/SMAD4 autophagy pathways, thereby attenuating tumor growth." (PMID 39459634, 2024). "Smad4 is important in preventing tumor growth and plays a key role in pancreas health." (PMID 39596873, 2024). "In the early stages of cancer, SMAD4 contributes to anti-tumor immunosurveillance by NK cells." (PMID 39273395, 2024). "Furthermore, NGS for tumor protein 53, SMAD4, mammalian target rapamycin, and CTNNB1 genes are useful in identifying advanced neoplasia when combined with GNAS/MAPK mutation with a sensitivity and specificity of 88% and 98%, respectively." (PMID 38731128, 2024). "Of additional note, the loss of SMAD4 has been demonstrated to subvert the protective, tumor-suppressive function of BMP signaling, converting it into a tumor-promoting entity, underscoring the delicate balance and functional duality of BMP signaling in intestinal homeostasis and disease." (PMID 39388072, 2024). "Thus, Smad4 in S100A4+ macrophages plays a tumor-inhibiting role in CAC development and supports its use as a prognostic marker in CRC patients." (PMID 39664586, 2024). "SMAD4 is a member of the TGF-β pathway acting as a tumor suppressor." (PMID 38607041, 2024). "Furthermore, western blot analysis of tumor tissues confirmed that myeloid cell-specific Smad4 ablation promoted STAT6 phosphorylation, whereas blocking Fabp2 reversed this phenomenon." (PMID 39664586, 2024). "This enhanced tumor growth persisted when low levels of SMAD4 expression were enforced, however, in the presence of BMP4, the time required for 468-GIL tumors expressing SMAD4 to reach 400 mm3 was notably longer (60 days) compared to that for the SMAD4-null tumors (40 days)." (PMID 38689334, 2024).